CXCL10 (C-X-C motif chemokine ligand 10)
Diseases named in the same sentence as CXCL10 in open-access papers (continued):
Sharing a sentence is not in itself a finding about the gene and the disease.
cancer (continued). "CXCL10, also known as interferon γ-induced protein 10 (IP-10), is strongly induced by IFNs (IFN-α, IFN-β but mostly IFN-γ), as well as by the LPS/NF-κB axis and other immune stimulants in monocytes, endothelial cells, fibroblasts and cancer cells." (PMID 36912171, 2023). "CXC motif chemokine ligand 10 (CXCL10) is a member of the CXC chemokine family, which is suggested to have pleiotropic effects on a variety of biological processes including immunity, angiogenesis, and cancer metastasis." (PMID 36818656, 2023). "Therefore, CXCL9, CXCL10, and the CXCL11/CXCR3 axis have been regarded as potential cancer immune therapy targets." (PMID 35935945, 2022). "Consequently, CXCL9 and CXCL10 promote lymphocyte infiltration into HCC and thus influence cancer immunology." (PMID 35897689, 2022). "Cancer cells often maintain abundant damaged DNA, which can also stimulate STING-dependent induction of IFNs and other anti-tumor cytokines/chemokines, including CXCL10 and CCL5." (PMID 36498833, 2022). "As with TCGA Pan-Cancer Atlas data, patients with below-median PI24 scores expressed high levels of immunoglobulin genes, CD8A, and chemokine genes (CCL4, CCL5, and CXCL10), and had significantly higher PFS and OS rates (P = 0.00041 and P = 0.0011, respectively)." (PMID 36099049, 2022). "Along the paclitaxel-mediated ICD, the cancer cell autonomous TLR4 signaling is essential to the release of DAMPs, which led, in an autocrine manner, to the activation of the NF-κB-mediated CCL2 transcription, together with CXCL10." (PMID 36429101, 2022). "Moreover, the immunogenic dying cancer cells were proposed to trigger a pathogen response-like chemokine signature, the CXCL1, CCL2 and CXCL10 co-release." (PMID 36429101, 2022). "In addition, correlative studies in clinical trials can mechanistically explore the role of eosinophils in cancer immunotherapy by measuring baseline and on-treatment chemokines, such as CCL5/CXCL9/CXCL10/CCL11." (PMID 35954493, 2022). "Inhibitor of MAPK pathway using mitogen-activated protein kinase (MEK) inhibitor in combination with chemotherapy triggers mitophagy of cancer cells, which induces the release of mitochondrial DNA that interact with Toll Like receptor 9 (TLR9) to promote the production of the chemokine CXCL10." (PMID 35529902, 2022). "Importantly, CXCL10 and CXCL9 are highly expressed by human cancer cells, and this expression is correlated with a good prognosis." (PMID 34944943, 2021). "Interferon-γ (IFN-γ) is the major inducer of three CXCR3 ligands, monokine induced by IFN-γ (MIG)/CXCL9, 10 kDa IFN-γ-induced protein (IP-10)/CXCL10 and IFN-inducible T cell α chemoattractant (I-TAC)/CXCL11 in mainly endothelial cells, monocytes, fibroblasts, and cancer cells." (PMID 34503058, 2021). "Reduced levels of CXCL9 and CXCL10 are correlated with the immunosuppressive microenvironment, negative responses to ICIs, and poor prognosis among cancer patients." (PMID 34855841, 2021). "Although recent studies have found that in different types of cancer, patients with high expression of CXCL10 have a better clinical prognosis 46-48, but no one has explained the molecular mechanism of CXCL10 high expression." (PMID 34158843, 2021). "There was no significant impact on CXCL10 in macrophage cultures, but there was a strong increase in the protein level of cancer specimens after coincubation with PIC and curcumin." (PMID 33809574, 2021). "We thus explored the CXCL10 expression signature and ICB-related genes across the cancer types." (PMID 34158843, 2021). "It suggests that SAA1, CXCL10, CCR5, CCL19, CXCL11, CXCL13, and CCL5 have important function in immunotherapy for cancer patients, and may be used as key regulator genes of immunotherapy." (PMID 34093667, 2021). "Among CD68+CD163+ TAMs also expressing the recently identified TREM2 marker, we could identify a CXCL10+IRF1+STAT1+ M1-type Mφ population (Cluster 9) shared between all cancer types." (PMID 34220848, 2021).
cancer (continued). "CXCL10 is a ligand of the CXC chemokine receptor-3 (CXCR3) and is predominantly expressed by T helper cells (Th cells), cytotoxic T lymphocytes (CTLs), dendritic cells, macrophages, natural killer cells (NKs), as well as some epithelial and cancer cells." (PMID 34422627, 2021). "CXCL10 and CXCL11 increase the number of CXCR3-expressing cancer stem cells in BRCA cell lines." (PMID 34067089, 2021). "The levels of CXCL10 and CXCL11 were limited under homeostatic conditions but could be secreted by cancer cells, endotheliocytes, leukocytes, and fibroblasts in response to different stimulants." (PMID 34944392, 2021). "In this study, we found that the inhibition of GLS by compound 968 could increase the expression of CXCL10 and CXCL11 by cancer cells." (PMID 34944392, 2021). "IHC assay was conducted for identifying CXCL10 levels within NPC samples and non-carcinoma samples." (PMID 34544905, 2021). "Also, the transcriptional expressions of CXCLs family members were correlated with patients' individual cancer stages and nodal metastasis status, especially for CXCL2, CXCL3, CXCL4, CXCL7, CXCL9, CXCL10, CXCL11, and CXCL12." (PMID 32963527, 2020). "Cytokines that may be dysregulated in cancer include IL-12, IL-15, IL-24, CXCL9, CXCL10, and CXCL11." (PMID 33419310, 2020). "Therefore, some chemokines such as CCL2, CXCL10, and CX3CL1/CX3CR1 can be either favorable or unfavorable cancer prognostic factors depending on the cancer types." (PMID 31991604, 2020). "To address whether both CXCL9 and CXCL10 contribute to oncosphere formation and lung metastasis, we overexpressed the genes individually in MDA or SUM cancer cells." (PMID 32198421, 2020). "As we found levels of the cytokines CCL5, CXCL9, CXCL10, and IL16 to indicate high CTL score across multiple cancers, we hypothesized that ATM in its role as a signal transducer may be promoting the transcription of these cytokines." (PMID 29615613, 2018). "Therefore, results suggest that CXCL10 expression is highly induced by an inflammatory stimulus, such as IFN-ɣ, in normal and cancer thyroid epithelial cells." (PMID 29416784, 2018). "Recently, CXCL10 was reported to have higher expression levels in CML patients and may be involved in cancer cell growth and metastasis." (PMID 29649138, 2018). "Most recently, this concept has been shown to be important in neutrophil-based anticancer activity, where apoptotic cancer cells release epigenetically regulated cytokines such as CXCL1, CXCL10, and CCL2, driving nucleic acid-elicited phagocytosis of dying cancer cells by neutrophils." (PMID 29666625, 2018). "Using cancer-related pathway probes, we showed that STAT3 inhibited the expression of several IFN response genes in GICs, such as the chemokines CXCL9, CXCL10 and CXCL11, which is consistent with the finding that STAT3 can inhibit the expression of IFN response genes." (PMID 29774125, 2018). "Our results offer additional confirmation to our speculation that MDM2 can shift the balance of the intracellular events in cancer cells towards pro-angiogenic mechanisms through up-regulation of TNF-α, MMP9, and CXCL10." (PMID 29748481, 2018). "Our results suggest that increased TLR3 expression and TLR3-mediated CXCL10 induction is an attribute of cancer IECs rather than healthy IECs." (PMID 28717003, 2017). "Cytokines could reinforce the inflammatory milieu by inducing chemokine production by TC cells (e.g., INF-γ and TNF-α induce CXCL10/IP-10 production in primary human PTC and ATC cells) and by activating antiapoptotic signaling in cancer cells." (PMID 26379707, 2015). "Genetically knocking out TLR3 or the IFN-α/β receptor (IFNAR) in cancer cells ablated this protection, an effect that could be reversed by administering recombinant type I IFN or CXCL10 in the respective knockouts." (PMID 26486085, 2015).
cancer (continued). "CXCL10 is another pro-inflammatory chemokine that is released as a result of interferon gamma (IFN-γ) production and is responsible for monocyte and macrophage recruitment as well as some anti-cancer activities." (PMID 24736642, 2014). "Both CXCL10 and TNFSF10 have been shown to drive numerous human cancers into senescence." (PMID 23853104, 2013). "Thus, CXCL10 exerts both pro- and anti-tumoral effects in the TME and the effects may be dependent on the type of cancer." (PMID 40589738, 2025). "Notably, chemokines like CXCL9, CXCL10, and CXCL11 are primarily produced by a variety of cell types, including monocytes, endothelial cells, fibroblasts, and cancer cells, in response to IFN-γ, and this response is further amplified by TNF-α, highlighting their role as pro-inflammatory cytokines." (PMID 40227454, 2025). "Indeed, we found that most cancer cell lines failed to induce CXCL10 when treated with STINGa, yet they became responsive to STINGa in the presence of conditioned media (CM) collected from untreated PBMC cultures." (PMID 38992037, 2024). "Furthermore, CD11b-ADC, which directly delivers STINGa only into myeloid cells, induced type III IFNs in STING WT but not in STING KO SKBR3 cell co-cultures, whereas CXCL10 production was not affected by STING deletion in cancer cells." (PMID 38992037, 2024). "The proinflammatory cytokines IFNβ1 and CXCL10 were also elicited by low-dose TLC388 (0.5-1.0 μM), indicating that TLC388 has a superior ability to activate STING-mediated IFN-I production, thereby enhancing cancer immunogenicity, especially in cells with low immunogenicity." (PMID 38564022, 2024). "As previously reported the CXCL10 active ratio was independent of cancer stage suggesting it may assist in the differentiation of benign disease from early-stage malignancy." (PMID 37958440, 2023). "In accordance with the reported immunosuppressive effect of cancer cells on macrophages in the TME, incubation of the RAW 264.7 macrophages in ID8 CM resulted in increased production of the immunosuppressive cytokine IL-10 and decreased production of the M1 phenotype-related chemokine CXCL10." (PMID 37376134, 2023). "In contrast, FMRP‐KO cancer cells could recruit CCR5+ and CXCR4+ CD8 T cells to indirectly kill cancer cells by promoting M1 macrophages to secrete proinflammatory chemokines CCL5, CXCL9, and CXCL10." (PMID 36968189, 2023). "However, the exact mechanism linking cancer-related fatigue in AML patients with CXCL10 has not been fully understood." (PMID 37760523, 2023). "Compared with previous studies that investigated the value of TMEscore in other cancers, our study constructed a four-gene TME signature using TMEscore-related genes (CXCL10, LZTS2, IDO1, and MAB21L2), making it easy for clinicians to assess patients who might belong to the TME-H or TME-L signature." (PMID 37596528, 2023). "Furthermore, both CXCL10 and STAT2 are involved in the induction of apoptosis in cancer cells." (PMID 35207629, 2022). "However, we discovered that ATS may have an immunosuppressive effect by downregulating the expression of key chemokines such as CXCL9, CXCL10, and CXCR3, and therefore decreasing the cancer immunity." (PMID 36302799, 2022). "However, these two studies were focused towards the expression analysis of ACE2 and TMPRSS2 rather than CXCL10, which is an important inflammatory cytokine that plays an active role in cancer metastasis." (PMID 36239108, 2022). "CXCL10 and CXCL11 are ligands of chemokine CXCR3, which can regulate the migration, differentiation and activation of immune cells, and are related to the selective migration and linear development of CD4 + and CD8 + T cells, thereby affecting the therapeutic effect of cancer." (PMID 35087563, 2021).
cancer (continued). "However, we found that Siglec15 may exert an immunosuppressive function by comprehensively downregulating the expression of critical immunomodulators such as CXCL9, CXCL10, and CXCR3, and subsequently downregulating the activities of the cancer-immunity cycle." (PMID 33537076, 2021). "In the process of module analysis and characteristic molecular screening, we selected two characteristic modules and 10 characteristic molecules (PTPRC, CD2, CD69, IRF8, CCR7, CCL5, il2rb, CXCL10, CCR5, TBX21), which could be used as biomarkers of cancer stem-like cells for GIST patients." (PMID 34925310, 2021). "However, in some types of cancer cells, such as acute myeloid leukaemia cells, chronic hypoxia does not change the expression of CXCL10." (PMID 33467722, 2021). "CXCL9, CXCL10, and CXCL11 (C-X-C motif chemokine ligand 9, 10, and 11, respectively) are chemokines that share functions as ligands of CCR3, stimulating antitumoral immunity, but they can also promote proliferation and metastasis in cancer cells in an autocrine pathway, as recently reviewed." (PMID 32117120, 2020). "Notably, CXCL9, CXCL10, and IFNG had significantly higher expression levels in the higher-TMB subtype of at least 10 cancer types, while had significantly higher expression levels in the lower-TMB subtype of at most 4 cancer types." (PMID 30634925, 2019). "Interestingly, both these effective combinations showed at least partial selectivity in inducing CXCL10 (rather than CCL22) in cancer tissues." (PMID 25806105, 2015). "However, our findings indicate that plasma CXCL10 levels do not reflect the local level of CXCL10 in cancer tissue but are correlated well with disease stage." (PMID 24748971, 2014). "These associations between therapy resistance and STAT1 in cancer may explain the association of STAT1 levels with higher CCL2 and CXCL10 and the apparent lack of therapy sensitivity in high STAT1 patients." (PMID 24460726, 2014). "The levels of plasma CXCL10 from 104 patients were significantly (P<0.01) higher compared to those in control subjects; however, the plasma levels were not correlated to the levels in cancer tissue (data not shown)." (PMID 24748971, 2014). "In addition, treatment of cancer cell monocultures with STINGa in the presence of CM collected either from the primary human PBMC or isolated primary human monocyte cultures, but not THP1 malignant monocytic cell cultures, markedly induced CXCL10 cytokine production." (PMID 38992037, 2024). "Among them, interferon (IFN) inducible CXC chemokine, CXCL9 (Mig), CXCL10 (IP-10) and CXCL11 (I-TAC), are multifunctional chemokine orchestrating immunity and angiogenesis via shared G-protein coupled receptor CXCR3, thus, these ligands might play a crucial role in cancer." (PMID 26910919, 2016). "Similarly, vital immune checkpoint genes such as HAVR2, CD274, CTLA4, ITGB2, ICAM1, CCL5, CXCL10 all exhibited robust correlation with IFI30, and this immunotherapy might, in the future, establish a bond with IFI30, bringing new opportunities for cancer treatment." (PMID 39925804, 2025). "Consistently, fresh human WBCs cultured on HER2-coated plates in the absence of cancer cells failed to produce type III IFNs in response to HER2-ADC treatment, despite significant levels of CXCL10 production." (PMID 38992037, 2024). "Importantly, CXCL10 measurement was largely independent of stage, suggesting that it could provide a useful addition to standard testing workflows to improve triage for surgical staging of patients with early, low-volume cancers." (PMID 37958440, 2023). "Fibrocytes secrete only IL23 and IFNγ, which were suppressed upon co-culture, whereas cancer cells or fibrocytes secrete CCL5, IL-1ra, CD54, CXCL10, MIF, CXCL1, IL-6, and IL-8, which was not affected by co-culture." (PMID 36241617, 2022). "In line with this, CM from CXCR3+ cancer cells, but not from CXCR3− cells, induced high CXCL10 expression in mouse and human lung fibroblasts." (PMID 32198421, 2020).
cancer (continued). "PTGS2, FN1, CXCL9, CXCL10, ZIC2 e OVOL1 podem desempenhar alguns papéis no carcinoma nasofaríngeo." (PMID 27765529, 2017). "To determine the source of CXCL10 production, we performed ELISA assays on culture supernatants and confirmed that CXCL10 secretion was significantly reduced in MTAP-KO cells, indicating that cancer cells, not PBMCs, were the primary contributors to CXCL10 levels." (PMID 41246302, 2025). "Several genes were also, however, inconsistent with the mouse model data including CCL5, CCL20, CCL22, CCL28, CXCL10, and PDL2, suggesting that these features may not be as robustly tissue-specific across different primary cancers." (PMID 33985562, 2021). "Furthermore, we provided new insights that CXCL10 through TLR4, instead of CXCR3, mobilized monocytic MDSCs, but not granulocytic MDSCs, to the liver for facilitating cancer recurrence using CXCL10−/−, CXCR3−/− and TLR4−/− mice." (PMID 33990548, 2021). "ZIC2 e OVOL1 podem funcionar no carcinoma nasofaríngeo almejando-se de maneira significativa os genes suprarregulados (como o PTGS2, FN1, CXCL9 e CXCL10) na rede reguladora de fator de transcrição - genes diferencialmente expressos (p.ex., ZIC2→PTGS2 e OVOL1→CXCL10)." (PMID 27765529, 2017). "When the cells were treated with a combination of cetuximab and MEK or JNK, the expression levels of CCL5, CXCL9 and CXCL10 increased, confirming that not one but multiple pathways downstream of the EGFR act in concert to block IFNγ/TNFα -induced chemokine expression by these cancer cell lines." (PMID 30192802, 2018).